SNRPE (small nuclear ribonucleoprotein polypeptide E)
Description:
Plays a role in pre-mRNA splicing as a core component of the spliceosomal U1, U2, U4 and U5 small nuclear ribonucleoproteins (snRNPs), the building blocks of the spliceosome. Component of both the pre-catalytic spliceosome B complex and activated spliceosome C complexes. As a component of the minor spliceosome, involved in the splicing of U12-type introns in pre-mRNAs. As part of the U7 snRNP it is involved in histone 3'-end processing.
Synonyms: snRNP-E; Sm-E; SmE; HYPT11
Tractability: Small molecule: a structure with a bound ligand is known; it has a binding pocket of medium quality. PROTAC: ubiquitination databases record sites on it; its protein half-life has been measured.
Gene: Protein-coding gene on chromosome 1 (203,861,598 to 203,871,152, forward strand). Ensembl gene ENSG00000182004.
Subcellular location: Cytoplasm, cytosol; Nucleus
Pathways (Reactome):
Metabolism of RNA: SLBP Dependent Processing of Replication-Dependent Histone Pre-mRNAs; SLBP independent Processing of Histone Pre-mRNAs; mRNA Polyadenylation; mRNA Splicing - Major Pathway; mRNA Splicing - Minor Pathway; snRNP Assembly
Disease: Dengue Virus-Host Interactions; SARS-CoV-2 modulates host translation machinery
Chromatin organization: CHD1 and CHD2 subfamily
Gene expression (Transcription): RNA Polymerase II Transcription Termination
Gene Ontology:
Molecular function: protein binding; RNA binding
Biological process: mRNA splicing, via spliceosome; spliceosomal snRNP assembly; 7-methylguanosine cap hypermethylation; negative regulation of mRNA splicing, via spliceosome; nuclear histone mRNA catabolic process; spliceosomal complex assembly; spliceosomal tri-snRNP complex assembly; spliceosome conformational change to release U4 (or U4atac) and U1 (or U11); U2-type prespliceosome assembly
Cellular component: catalytic step 2 spliceosome; cytosol; methylosome; nucleus; pICln-Sm protein complex; post-mRNA release spliceosomal complex; post-spliceosomal complex; precatalytic spliceosome; SMN-Sm protein complex; spliceosomal complex; telomerase holoenzyme complex; U1 snRNP; U11/U12 snRNP; U12-type catalytic step 2 spliceosome; U12-type precatalytic spliceosome; U12-type spliceosomal complex; U2-type catalytic step 1 spliceosome; U2-type catalytic step 2 spliceosome; U2-type precatalytic spliceosome; U2-type spliceosomal complex; U4 snRNP; U4/U6 x U5 tri-snRNP complex; U7 snRNP; nucleoplasm; small nuclear ribonucleoprotein complex; and 6 more
Genetic constraint (gnomAD): Loss-of-function variants: 0 observed, 3.1 expected, observed/expected ratio (o/e) 0, 90% interval 0 to 0.95. That is too few expected variants to judge how well the gene tolerates losing a copy. Missense variants: 10 observed, 27.76 expected, observed/expected ratio (o/e) 0.36, 90% interval 0.22 to 0.61. Synonymous variants: 8 observed, 9.59 expected, observed/expected ratio (o/e) 0.83, 90% interval 0.49 to 1.49.
Homologues: Orthologues: mouse Snrpe (100% identical), zebrafish snrpe (95% identical), Drosophila melanogaster SmE (75% identical), tropical clawed frog snrpe (73% identical), Caenorhabditis elegans snr-6 (61% identical).
Diseases named in the same sentence as SNRPE in open-access papers:
SNRPE is named in the same sentence as 32 diseases in open-access papers, as found by Europe PMC text mining. Sharing a sentence is not in itself a finding about the gene and the disease. The quoted sentences say what the papers report.
breast carcinoma (5 papers, 2016 to 2025). "We also differentiated SNRPD1 and SNRPE regarding their roles on breast cancer progression and onco-therapeutic implications." (PMID 37098488, 2023). "SNRPD1 and SNRPE, among other Sm proteins, were shown overexpressed in a subset of highly aggressive breast cancers, and were proposed as novel onco-therapeutic targets since the depletion of either one halted breast cancer growth without affecting the quasi-normal MCF10A cells." (PMID 37098488, 2023). "Provided with the different roles of SNRPD1 and SNRPE in cell migrative abilities and drug sensitivities that may drive their differential prognostic values on breast cancer survival, we examined their correlated genes to investigate differences on their molecular mechanisms." (PMID 37098488, 2023). "Particularly, PABPC1 presented the second highest reduction in the MTT assay next to small nuclear ribonucleoprotein polypeptide E (SNRPE), and its transcript level was elevated in many cancer types including breast cancer." (PMID 36923539, 2023). "Our results suggest the prognostic value of SNRPD1 but not SNRPE on breast cancer survival, and warrant the use of SNPRD1 in the onco-therapeutic design given its unveiled roles in sensitizing TNBC cells to anthracycline-type of chemotherapies." (PMID 37098488, 2023).
lung carcinoma (4 papers, 2012 to 2025). "A prognostic score based on the expression of ADAR2 and four additional RNA metabolism-related genes (MARS, RAE1, SNRPB and SNRPE) can stratify lung cancer patients into high and low risk groups for cancer death." (PMID 22876301, 2012). "Specifically, depletion of small nuclear ribonucleoprotein polypeptide E (SNRPE) led to reduced cell viability in lung cancer cell lines." (PMID 30679557, 2019).
microcephaly (3 papers, 2019 to 2025). A congenital or acquired developmental disorder in which the circumference of the head is smaller than normal for the person's age and sex. "Our study links defects in the SNRPE/SmE gene to microcephaly and provides the new pathogenic mechanism for microcephaly." (PMID 31671093, 2019). "Our study suggest that the identified missense mutation in SNRPE disturbs appropriate spatiotemporal gene expression in the brain through aberrant mRNA splicing, which is likely to cause the microcephaly phenotype." (PMID 31671093, 2019). "Furthermore, a recent study shows SNRPE variants causing congenital non-syndromic microcephaly; this gene encodes SmE proteins involved in the assembly of the spliceosome complex." (PMID 36831309, 2023). "Finally, although we identified the SNRPE mutation (c.65T>C (p.Phe22Ser)) from only one patient, the biochemical and zebrafish data provide strong evidence to link this mutation to the microcephaly phenotype manifested in this patient." (PMID 31671093, 2019). "Together, our study links defects in the SNRPE gene to microcephaly and suggests that alterations of cellular splicing of specific mRNAs such as EMX2 results in the neurological phenotype of the disease." (PMID 31671093, 2019). "Here we report the identification of a de novo heterozygous missense mutation in the SNRPE gene (c.65T>C (p.Phe22Ser)) in a patient with non-syndromal primary (congenital) microcephaly and intellectual disability." (PMID 31671093, 2019). "Here we report the identification of a de novo heterozygous missense mutation in the SNRPE/SmE gene in a patient with non-syndromal primary (congenital) microcephaly and intellectual disability." (PMID 31671093, 2019).
prostate carcinoma (3 papers, 2019 to 2022). A carcinoma that arises from epithelial cells of the prostate gland. "SNRPE protein is a core component of Sm proteins, which has been reported in some malignancies, including bladder cancer, prostate cancer, hepatocellular carcinoma, and non-small cell lung cancer." (PMID 35356432, 2022). "In addition, SNRPE was found to be involved in cell proliferation and the progression of prostate cancer by regulating androgen receptor mRNA expression in cells." (PMID 36371223, 2022). "SNRPE (small nuclear ribonucleoprotein polypeptide E) has oncogenic effects in prostate cancer." (PMID 30808328, 2019).
lung adenocarcinoma (2 papers, 2024 to 2025). A carcinoma that arises from the lung and is characterized by the presence of malignant glandular epithelial cells. "Finally, by integrating the results of PPI network analysis and one-way COX regression analysis, we identified six RBPs that are both DEGs and associated with lung adenocarcinoma prognosis—IGF2BP3, SNRPE, GAPDH, MRPL12, MRPL15, and INTS8, with IGF2BP3 being the most differentially expressed." (PMID 40801655, 2025).
asthma (1 paper, 2021). "Also, in the context of development of severe asthma, KEGG enrichment of the spliceosome (mRNAs; SF3A1, SNRPE, SF3B4) has been observed." (PMID 34068174, 2021).
ovarian carcinoma (1 paper, 2024). A malignant neoplasm originating from the surface ovarian epithelium. "Furthermore, our findings confirmed that the overexpression of SNRPE notably boosted the proliferation and invasion abilities of ovarian cancer cells, indicating its potential as a therapeutic target for this type of cancer." (PMID 39726597, 2024). "Significantly, SNRPE knockdown markedly suppressed cell proliferation in both OVCAR-3 and A2780 cell lines, underscoring SNRPE’s contribution to promoting ovarian cancer cell growth." (PMID 39726597, 2024).
cancer (15 papers, 2008 to 2025). A tumor composed of atypical neoplastic, often pleomorphic cells that invade other tissues. "We conducted in silico analysis at gene expression and genetic levels to differentiate the clinical relevance of SNRPD1 and SNRPE, and explored their differential functionalities and molecular mechanistic associations with cancer in vitro." (PMID 37098488, 2023). "Interestingly, increased percentage of ALDH1, a cancer stem cell marker, was observed in cells deficient of SNRPE expression, suggestive of the suppressive role of SNRPE on cancer stemness that neutralizes its promotive role on cancer cell proliferation." (PMID 37098488, 2023). "Targeting the deregulated spliceosome core machinery in various cancer cell types, via the genetic inhibition of SNRPE, or SNRPD1, triggers MTOR blockade, which is well known to cause autophagy induction." (PMID 35585060, 2022). "The altered expression level of hub SFs has been reported in multiple types of cancer, such as YBX1, SART1, SNRPE, and SF3B4." (PMID 33101358, 2020). "Remarkably, the oncogenes shown are Known to decrease apoptosis that could result in cancer cell survival like YBX1, SNRPE, RRM2, and COX6B1." (PMID 41347211, 2025). "In malignant tumor cells, knockdown of the core spliceosome components small nuclear ribonucleoprotein polypeptide E and small nuclear ribonucleoprotein D1 polypeptide resulted in cancer cell death through autophagy rather than apoptosis." (PMID 33937013, 2021). "Interestingly, the analysis revealed that 7 targets (SF3B1, SF3B3, SNRPA, SNRPE, SNRPF, HNRNPA3 and EFTUD2) are physically interacting proteins within the spliceosome complex, suggesting that JA might regulate the cancer spliceosome to induce tumor-specific cell death." (PMID 28198434, 2017).
tumor (8 papers, 2017 to 2025). "An OV single-cell RNA dataset was amassed and scrutinized to uncover the role of Small Nuclear Ribonucleoprotein Polypeptide E (SNRPE) in the tumor microenvironment (TME)." (PMID 39726597, 2024). "The mRNA levels of YBX1 and SNRPE were increased in tumor samples in the two microarrays, although the expression levels only showed statistically significant differences in GSE19750." (PMID 33101358, 2020). "Of note, a pivotal gene, SNRPE, was identified as having a promoting effect on tumor growth." (PMID 39726597, 2024).
SNRPE also shares sentences with these, for which no sentence is quoted: Cerebro-costo-mandibular syndrome (2 papers); hepatocellular carcinoma (2); hypotrichosis (2); infection (2); non-small cell lung carcinoma (2); Adrenocortical Carcinoma (1); Astrocytoma (1); bladder cancer (1); breast tumor (1); colon cancer (1); ectodermal dysplasia (1); endometrial cancer (1); esophageal cancer (1); glioblastoma (1); head and neck squamous cell carcinoma (1); hypotrichosis simplex (1); Intellectual disability (1); Kidney (1); mandibulofacial dysostosis (1); melanoma (1); Pheochromocytoma and Paraganglioma (1); renal carcinoma (1); Verheij syndrome (1).